AMACR (alpha-methylacyl-CoA racemase)
Diseases named in the same sentence as AMACR in open-access papers (continued):
Sharing a sentence is not in itself a finding about the gene and the disease.
glioblastoma (2 papers, 2020). The most malignant astrocytic tumor (WHO grade IV). "Bioinformatic analysis showed that high mRNA levels of AMACR were significantly associated with poor survival in glioblastoma." (PMID 33154941, 2020). "Quantitative real-time PCR analysis with glioblastoma cell lines also showed that the AMACR mRNA level was increased in U87-MG, U251-MG, and U343-MGcells compared to HEK293A cells." (PMID 33154941, 2020). "FPKM values were noticeably higher in U87-MG cells (2.66) and U251-MG cells (3.62) than in the cerebral cortex (1.56), demonstrating that AMACR transcription is enhanced in glioblastoma cells." (PMID 33154941, 2020). "We also confirmed the expression of AMACR in human glioblastoma cell lines (U87-MG, U251-MG, U343-MG, and U373-MG)." (PMID 32760737, 2020). "Interestingly, AMACR was located in both the nucleus and cytosol in a dot-like pattern, indicating that AMACR showed ubiquitous localization in glioblastoma cells." (PMID 33154941, 2020). "In this study, AMACR appeared to be involved in glioblastoma." (PMID 33154941, 2020). "The protein and mRNA levels of AMACR were highly elevated in glioblastoma." (PMID 33154941, 2020). "mRNA levels of AMACR in glioblastoma showed >60-fold higher expression than the control." (PMID 32760737, 2020). "In summary, these findings indicate that AMACR expression is increased in a glioblastoma cell line and glioma patients, suggesting that AMACR might be a potential diagnostic marker and therapeutic target for cancer, including glioma." (PMID 33154941, 2020). "As expected, expression of AMACR in GBM tissues was drastically increased compared to normal tissues, suggesting that AMACR expression is upregulated in glioblastoma patients." (PMID 33154941, 2020).
glioma (2 papers, 2019 to 2020). A benign or malignant brain and spinal cord tumor that arises from glial cells (astrocytes, oligodendrocytes, ependymal cells). "Protein levels of AMACR were increased in glioma patients, and mRNA and protein levels of AMACR were increased in glioma cell lines." (PMID 33154941, 2020). "Comprehensive analysis of the public REMBRANDT GBM dataset also confirmed that the level of AMACR expression was correlated with the clinical prognosis of glioma patients." (PMID 33154941, 2020). "Additionally, analysis based on 1,018 Chinese glioma patients suggested that CELF5 (P < 0.001), GSG1L (P = 0.002), AMACR (P < 0.001), CYP27A1 (P < 0.001), CYP46A1 (P < 0.001), and CH25H (P = 0.046) were all prognostic indicators in Kaplan-Meier survival analysis." (PMID 32117422, 2019).
liver fibrosis (2 papers, 2024 to 2025). "Moreover, HCC in AMACR deficiency has been previously reported, with evidence suggesting a risk of liver fibrosis, cirrhosis, and eventual HCC in affected patients." (PMID 40643170, 2025).
metastatic carcinoma (2 papers, 2016 to 2023). A carcinoma which has spread from the original site of growth to another anatomic site. "In cases suspected for chordoma, where the possibility of metastatic carcinoma of prostatic, hepatic, renal or colorectal origin is considered, AMACR and β-catenin IHC stains cannot assist the differential diagnosis since all of these tumours express both markers." (PMID 26888362, 2016). "In the case of metastatic carcinoma, AMACR could not be a reliable marker for the distinction of female genital tract CCC." (PMID 37383161, 2023).
neuroendocrine neoplasms of (2 papers, 2012 to 2013). "As yet, only two reports have considered AMACR expression in neuroendocrine neoplasms, and only five reports mention AMACR expression in gastric neoplasms." (PMID 22782380, 2012). "There are only two papers showing significant AMACR expression in neuroendocrine neoplasms of the lung." (PMID 22782380, 2012). "Although AMACR is expressed in numerous tumour types, its expression has never been studied in neuroendocrine neoplasms of the digestive system." (PMID 22782380, 2012).
ovarian clear cell cancer (2 papers, 2023 to 2024). An invasive malignant neoplasm that arises from the ovary and is characterized by a predominance of clear and hobnail malignant epithelial cells. "In ovarian clear-cell carcinoma, AMACR is significantly overexpressed, surpassing other forms of epithelial tumors." (PMID 40729263, 2024).
peroxisomal disorder (2 papers, 2018 to 2024). "Alpha-methylacyl-CoA racemase (AMACR) deficiency is an autosomal recessive peroxisomal disorder caused by pathogenetic variants in the AMACR gene that was first described in 2000." (PMID 39313810, 2024).
retinitis pigmentosa (2 papers, 2015 to 2024). Retinitis pigmentosa (RP) is an inherited retinal dystrophy leading to progressive loss of the photoreceptors and retinal pigment epithelium and resulting in blindness usually after several decades. "The median delay to diagnosis of AMACR deficiency after the diagnosis of retinitis pigmentosa was 24 years (range 0–33)." (PMID 39313810, 2024).
rhabdomyolysis (2 papers, 2024). Necrosis or disintegration of skeletal muscle often followed by myoglobinuria. "AMACR deficiency is an uncommon cause of rhabdomyolysis where only two cases have so far been reported." (PMID 39544692, 2024). "It remains therefore unknown whether AMACR deficiency can truly cause (recurrent) rhabdomyolysis or that these patients are more prone to a neuroleptic malignant syndrome due to neuroleptic medication." (PMID 39313810, 2024). "None of the patients in our cohort experienced rhabdomyolysis, so we cannot draw conclusions on this possible disease manifestation, except that this is most likely rare in AMACR deficiency." (PMID 39313810, 2024).
tubular adenoma (2 papers, 2009 to 2013). A usually polypoid neoplasm arising from the glandular epithelium. "It existed in histologically normal colonic glands and tubular adenomas with low AMACR expression and was absent in villous adenomas and all CCas expressing variable levels of AMACR." (PMID 19148275, 2009). "In general, AMACR immunostaining was negative to weak in normal cryptal and apical epithelia, as well as in tubular adenomas (TAs) with mild dysplasia." (PMID 19148275, 2009).
urachal adenocarcinomas (2 papers, 2018 to 2022). "Useful biomarkers of urachal adenocarcinomas, like alpha-methylacyl-CoA racemase (AMACR, p504s), CD15 (Leu-M1), carcinoembryonic antigen (CEA), CK34βE12 (high-molecular weight cytokeratin), GATA binding protein 3 (GATA3), mucin 2 (MUC2), and mucin 5AC (MUC5AC), should be taken into consideration." (PMID 36010242, 2022).
villous adenoma (2 papers, 2009 to 2013). An epithelial neoplasm morphologically characterized by the presence of a villous architectural pattern. "In contrast, villous adenomas (VAs), well- and moderately differentiated adenocarcinomas expressed high levels of AMACR." (PMID 19148275, 2009).
acinar adenocarcinoma (1 paper, 2012). "In areas of acinar adenocarcinoma, nuclear and cytoplasmic staining for p63 and CK5, respectively, was absent due to loss of basal cells, whilst the malignant glands showed gain of brown cytoplasmic granular staining indicating expression of AMACR." (PMID 22800084, 2012).
acinar adenocarcinoma of the prostate (1 paper, 2025). "Histopathological examination of the biopsy specimen confirmed acinar adenocarcinoma of the prostate (ICD-O 8140/3), with immunohistochemical staining showing p63 (−) and AMACR (+)." (PMID 40565112, 2025).
Barrett esophagus (1 paper, 2024). Esophageal lesion lined with columnar metaplastic epithelium which is flat or villiform. "However, there is a notable difference in AMACR expression between low- and high-grade dysplasia in Barrett’s esophagus." (PMID 39336516, 2024).
brain tumors (1 paper, 2020). "In this study, we investigated the potential of AMACR as a biomarker in brain tumors." (PMID 33154941, 2020). "However, the function of AMACR in brain tumors has not been investigated." (PMID 33154941, 2020).
celiac disease (1 paper, 2020). An autoimmune genetic disorder with an unknown pattern of inheritance that primarily affects the digestive tract. "Among them, there were two celiac disease-associated SBAs and four Spo-SBAs; worthy of note, none of the three Crohn’s disease-associated SBAs having a CK7−/CK20+/CDX2+/SATB2+ pattern expressed AMACR." (PMID 33228145, 2020).
chordoma (1 paper, 2016). Chordomas are rare malignant tumors arising from embryonic remnants of the notochord in axial skeleton. "If proven to be true, it is possible that our new finding of AMACR expression in chordomas is also associated with the Wnt pathway." (PMID 26888362, 2016). "In view of the reported association of chordomas with β-catenin staining and β-catenin with AMACR expression, we hypothesized that chordomas are associated with overexpression of AMACR." (PMID 26888362, 2016). "Following the IHC study that found presence of AMACR protein in the majority of the chordomas, we attempted to explore AMACR mRNA level in the same tumour samples." (PMID 26888362, 2016). "In our current study we have shown for the first time that chordomas express AMACR both at the protein as well as the mRNA level." (PMID 26888362, 2016). "Nonetheless, more studies are needed to substantiate our results and to identify the specific role of AMACR in chordoma." (PMID 26888362, 2016). "In all 5 successful chordoma cases, we have found the presence of AMACR mRNA." (PMID 26888362, 2016). "AMACR may serve as IHC marker of chordoma with differentiating ability comparable to that of β-catenin." (PMID 26888362, 2016). "In addition, AMACR mRNA level was assessed in 5 chordomas by RT-PCR and evaluated by comparative CT method." (PMID 26888362, 2016). "Our study is the first to report of AMACR expression in chordomas." (PMID 26888362, 2016). "Thus, AMACR may serve as IHC marker of chordoma in combination with the classical stains EMA and CKs, as it shows differentiating ability comparable to that of β-catenin." (PMID 26888362, 2016).
Crohn disease (1 paper, 2020). A gastrointestinal disorder characterized by chronic inflammation involving all layers of the intestinal wall, noncaseating granulomas affecting the intestinal wall and regional lymph nodes, and transmural fibrosis. "Importantly, none of these six cases occur in Crohn’s disease patients, while the four SATB2-positive Crohn’s disease-associated SBAs were all AMACR-negative, suggesting that an aberrant full-blown CRC-like phenotype is extremely rare in SBAs arising in Crohn’s patients." (PMID 33228145, 2020).
diabetes (1 paper, 2013). "In adipose tissue, we found not only a number of known cancer-related genes, like SOD2 or AMACR, but also diabetes- and obesity-related genes, like MTHFR or ADIPOR2." (PMID 23889843, 2013).
gastric adenocarcinoma (1 paper, 2024). "In conclusion, AMACR is a useful diagnostic marker for differentiating low-grade dysplasia from high-grade dysplasia and gastric adenocarcinoma." (PMID 39336516, 2024). "AMACR expression was observed in 26 of 39 cases of gastric dysplasia (66.7%) and in 17 of 40 cases of gastric adenocarcinomas (42.5%)." (PMID 39336516, 2024). "The expression rate of AMACR varies from 51.5% to 62.9% in gastric adenocarcinoma." (PMID 39336516, 2024).
gastric neoplasm (1 paper, 2012). A benign or malignant neoplasm involving the stomach. "Only a few studies have been performed regarding the prognostic significance of AMACR expression in gastric tumours, and it is still controversial." (PMID 22782380, 2012).
gastrointestinal stromal tumor (1 paper, 2014). "In conclusion, AMACR amplification is a mechanism driving increased mRNA and protein expression and conferring aggressiveness through heightened cell proliferation in gastrointestinal stromal tumors." (PMID 25473890, 2014). "AMACR-specific fluorescence in situ hybridization and immunohistochemistry were both informative in tissue microarray sections of 350 independent primary gastrointestinal stromal tumors, including 213 cases with confirmed KIT /PDGFRA genotypes." (PMID 25473890, 2014).
hepatocellular adenoma (1 paper, 2008). A benign epithelial neoplasm arising from the hepatocytes. "In their study, the cases of hepatocellular adenoma were not included and association between AMACR expression and clinic pathological parameters in HCC was not assessed." (PMID 18577240, 2008).
invasive carcinoma (1 paper, 2008). A carcinoma that is not confined to the epithelium, and has spread to the surrounding stroma. "In considering this relationship, sections containing HG-PIN without associated invasive carcinoma were of moderate intensity for claudin-4 and of low intensity for PSMA and AMACR." (PMID 18648369, 2008).
liver sarcoma (1 paper, 2024). A malignant soft tissue neoplasm that arises from the liver. "In the literature, a singular case of a 51‐year‐old patient diagnosed with AMACR deficiency was reported to have a liver tumor with a biopsy confirming a probable diagnosis of liver sarcoma." (PMID 39544692, 2024).
lymphoma (1 paper, 2020). A malignant (clonal) proliferation of B- lymphocytes or T- lymphocytes which involves the lymph nodes, bone marrow and/or extranodal sites. "There is continued interest in the association of AMACR expression and polymorphisms with cancer, as elevated AMACR protein or gene overexpression has been reported in various cancer tissues such as prostate, colon, rectum, ovaries, breast, bladder, lung, kidney, skin and lymphoma." (PMID 31436750, 2020).
mesenchymal neoplasms (1 paper, 2014). "The biological function of amplification-driven AMACR overexpression remains undefined in mesenchymal neoplasms." (PMID 25473890, 2014).
metabolic myopathy (1 paper, 2024). A group of rare inherited disorders characterized by a deficiency of enzymes that are involved in metabolic pathways that affect muscles. "After it was revealed that AMACR deficiency leads to rhabdomyolysis, the AMACR gene has been added to the rhabdomyolysis and metabolic myopathy panel." (PMID 39544692, 2024).
metastatic prostate carcinoma (1 paper, 2006). A carcinoma that arises from the prostate gland and has spread to other anatomic sites. "In this paper, we explore the expression of two proteins, i.e. EZH2 and AMACR known to be differentially expressed in non aggressive or localized tumors (class 1 or negative class) versus aggressive or metastatic prostate cancers (class 2 or positive class)." (PMID 17125514, 2006).
myxoid liposarcoma (1 paper, 2017). A liposarcoma characterized by the presence of round non-lipogenic primitive mesenchymal cells and small signet ring lipoblasts within a myxoid stoma with a branching vascular pattern. "Of the selected target genes, AMACR and TRIO in 5p and CDK4, HMGA2 and MDM2 in 12q showed significantly (p < 0.05) elevated expression in relation to myxoid liposarcomas." (PMID 28652867, 2017). "At RNA sequencing, significantly elevated expression, compared to myxoid liposarcomas, was seen for TRIO and AMACR in 5p and of CDK4, HMGA2 and MDM2 in 12q." (PMID 28652867, 2017).
neuroendocrine tumours of the stomach (1 paper, 2012).
oncocytoma (1 paper, 2015). "The further usage of an alpha-methyl CoA racemase (AMACR) antibody can be used as well for distinction between chromophobe RCC and oncocytoma." (PMID 25944973, 2015).
rectal adenocarcinomas (1 paper, 2021). "AMACR knockdown did not affect CDX2 expression, consistent with it being downstream of CDX2.To validate the relationship between CDX2 and AMACR in human CRCs, we next evaluated The Cancer Genome Atlas (TCGA) for CDX2 and AMACR in colon and rectal adenocarcinomas (COADREAD)." (PMID 33755595, 2021).
rubella (1 paper, 2023). A viral infection caused by the rubella virus. "In rubella, including five in whole blood (JAGN1, RRP12, RP11-452K12.7, CASP7, and AP3S2), four in the lung tissue (IL17RC, FAM86HP, AMACR, and RRP12), and four in the transformed fibroblast cells (PPP2R1B, C11orf1, DLAT, and TMEM117)." (PMID 37020999, 2023).
sarcoma (1 paper, 2017). A usually aggressive malignant neoplasm of the soft tissue or bone. "Genes located in 5p that have been suggested as possible amplicon targets in sarcomas include NKD2, TERT, IRX2, TRIO, AMACR, SKP2 and RICTOR." (PMID 28652867, 2017).
Sensorimotor neuropathy (1 paper, 2020). "Mutations in the AMACR gene are associated with sensorimotor neuropathy, muscle stiffness, and difficulty with coordination of movement." (PMID 32760737, 2020). "Other features of AMACR deficiency include weakness and loss of limb sensations due to nerve damage (sensorimotor neuropathy) and muscle stiffness (spasticity), and difficulty with coordination of movement (ataxia)." (PMID 32760737, 2020).
spindle cell carcinoma (1 paper, 2025). "Mucinous tubular and spindle cell carcinoma is also a biphasic tumor but can be distinguished by its prominent tubular component with extensive branching and interconnecting tubular architecture and is PAX8-, EMA-, CK7-, and AMACR-positive." (PMID 41268216, 2025).
tuberculosis (1 paper, 2024). A chronic, recurrent infection caused by the bacterium Mycobacterium tuberculosis. "In Mycobacterium tuberculosis (M. tuberculosis), the causative agent of tuberculosis (TB), α-methylacyl-CoA racemase is known as MCR (with 44% amino acid sequence identity with the human AMACR enzyme), and is of particular interest due to its involvement in cholesterol metabolism." (PMID 38540719, 2024).